LINC02774 (long independently transcribed non-coding RNA 2774)
Gene: Long non-coding RNA gene on chromosome 1 (243,917,316 to 244,047,551, forward strand). Ensembl gene ENSG00000226828.
Diseases named in the same sentence as LINC02774 in open-access papers:
LINC02774 is named in the same sentence as 3 diseases in open-access papers, as found by Europe PMC text mining. Sharing a sentence is not in itself a finding about the gene and the disease. The quoted sentences say what the papers report.
glioma (1 paper, 2023). A benign or malignant brain and spinal cord tumor that arises from glial cells (astrocytes, oligodendrocytes, ependymal cells). "Our research provides novel insights into the function of RIEMR‐associated LINC02774 as a tumor suppressor in glioma." (PMID 37701531, 2023). "Taken together, our findings demonstrate that LINC02774 inhibits cell proliferation, colonization, invasion, migration, and tumor growth, indicating that the RIEMR‐associated LINC02774 functions as a tumor suppressor in glioma." (PMID 37701531, 2023). "The expression of LINC02774 was detected in glioma cell lines (U251, U87‐MG, HS683), we found that HS683, derived from a Grade II patient, exhibited the highest expression of LINC02774." (PMID 37701531, 2023). "We found the downregulation of LINC02774 in glioma and decreased with the degree of malignant, with its expression showing a negative correlation with the relative index of enhanced magnetic resonance (RIEMR)." (PMID 37701531, 2023). "To further elucidate the function of LINC02774, we overexpressed LINC02774 in the U251 glioma cell line using lentiviral vectors." (PMID 37701531, 2023). "Second, although the expression of LINC02774 was accessed by the qRT‐PCR, additional tests are required to confirm its expression in glioma tissue." (PMID 37701531, 2023). "Similar to clinical tissue samples, LINC02774 was predominantly localized in the nucleus in glioma cell lines." (PMID 37701531, 2023). "The results shown that decreased the expression of LINC02774 in glioma was related to poor OS in patients, consistent with the TCGA data." (PMID 37701531, 2023). "Consistently, LINC02774 overexpression led to significant suppression of glioma sizes compared to U251‐Vector cells in the cerebral region." (PMID 37701531, 2023). "In subsequent validation experiments, overexpression of LINC02774 in U251 glioma cells significantly decreased the protein levels of HIF‐1α." (PMID 37701531, 2023). "Additionally, we performed in situ hybridization (ISH) on paraffin sections of glioma and observed the highest expression of LINC02774 in grade I glioma tissues, whereas the lowest expression was observed in grade IV glioma tissues." (PMID 37701531, 2023). "Furthermore, we found that overexpression of LINC02774 in U251 glioma cell lines led to decrease glucose consumption and lactate production, both under hypoxic and normoxic conditions." (PMID 37701531, 2023). "In conclusion, these findings reveal the role of RIEMR‐associated LINC02774, which relies on its neighbor gene, RP58, to regulate the hypoxia pathway as a novel tumor suppressor, suggesting its potential to be a prognostic marker and a molecular target for the therapy of glioma." (PMID 37701531, 2023). "To confirm the clinical significance of LINC02774 and examine whether the downstream targets of LINC02774 exhibit consistent changes in clinical glioma specimens, we analyzed the expression levels of LINC02774, PHD3, RP58, HIF‐1α, VEGF, and GLUT1 in different grades of glioma tissues." (PMID 37701531, 2023). "Analysis of LINC02774 and PHD3 mRNA in 695 glioma samples from the TCGA revealed a positive correlation between their expression levels." (PMID 37701531, 2023). "Additionally, based on the combination expression of LINC02774 and RP58, we demonstrated that glioma patients with high expression of both LINC02774 and RP58 tended to have longer survival, while patients with differential expression of the two genes had intermediate prognostic outcomes." (PMID 37701531, 2023).
cancer (1 paper, 2023). A tumor composed of atypical neoplastic, often pleomorphic cells that invade other tissues. "Coincidentally, the LINC02774 is located in the nucleus, which may perform a variety of roles in regulating the transcription of genes in cancer, such as transcriptional regulation in cis and in trans." (PMID 37701531, 2023).
tumor (1 paper, 2023). "We discovered that the depletion of LINC02774 expression significantly promoted the growth of tumor." (PMID 37701531, 2023).